BRAF (B-Raf proto-oncogene, serine/threonine kinase)
Diseases named in the same sentence as BRAF in open-access papers (continued):
Sharing a sentence is not in itself a finding about the gene and the disease.
melanoma (continued). "Although patients with BRAF-mutant melanoma have access to effective targeted treatments, these do not yet exist for BRAF-wt melanoma." (PMID 30428063, 2019). "Notably, no secondary mutations in RAS, MEK, and ERK that could rebound BRAF–MEK–ERK signaling were found in PLX4720-treated TFEBS142E tumors, and no concurrent activation of the Akt–mTOR signaling pathway, previously implicated in melanoma resistance, was detected in PLX4720-treated tumors." (PMID 30979895, 2019). "A recent study interrogating AMs by targeted deep sequencing identified two distinct subtypes of melanoma on acral sites: the BRAF mutant, similar to nonacral melanoma, and non-BRAF mutant." (PMID 31888295, 2019). "In this regard, the BRAF/MEK/ERK pathway represents an ideal candidate for targeting both oncogene and metabolism of certain types of tumors, especially melanomas, or may work successfully as a combinatorial regimen with other anticancer drugs." (PMID 30487597, 2019). "The BRAF kinase and the MAPK pathway are targets of current melanoma therapies." (PMID 30277012, 2019). "Inhibition of serine/threonine-protein kinase B-Raf (BRAF) and mitogen-activated protein kinase (MEK) in combination with A2AR provided a significant reduction of tumor progression and metastasis formation in a melanoma mouse model." (PMID 31739402, 2019). "In addition to lysine methyltransferases, two structurally unrelated H3K9 lysine demethylases, LSD1 and JMJD2C cooperate with BRAF to overcome oncogene-induced senescence (OIS) and contribute to the development of malignant melanoma." (PMID 31581557, 2019). "BRAF inhibition with Dabrafenib and MEK inhibition with Trametinib, either as monotherapy or in combination, lead to the suppression of phosphorylated ERK (pERK) in melanoma cells." (PMID 31467489, 2019). "Consistently, VEGF, histamine, and thrombin also promoted the migration of B16F10 melanoma cells through a monolayer of F/F, but not BRAF knockout endothelial cells, and this phenotype was rescued in BRAF/RAF1 knockout monolayers." (PMID 30828992, 2019). "Dogs have been used extensively to explore the role of new therapies such as vaccination for disease management, but with the exception of analysing driver genes such as BRAF and NRAS, little is known about the genetic landscape of this malignancy and how canine and human mucosal melanomas compare." (PMID 30664638, 2019). "BRAF inhibitors (Vemurafenib and Dabrafenib) and MEK inhibitors (Trametinib and Cobimetinib) have been approved by the FDA for treatment of advanced-stage melanoma patients with BRAF-V600-mutant." (PMID 30800130, 2019). "For example, vemurafenib dramatically improves the outcome of BRAFV600-mutant melanoma, whereas sorafenib, a weak BRAF inhibitor, does not have this effect." (PMID 31032221, 2019). "Notably, targeting the MAPK pathway by the BRAF inhibitor, vemurafenib, or the MEK inhibitor, dabrafenib, have been approved by the FDA for V600E mutant BRAF-harboring melanomas." (PMID 31752344, 2019). "The precise mechanisms through which BRAF and MEK inhibitors may down-regulate TF in melanoma cells are at present unknown." (PMID 31467489, 2019). "Thus, through TFEB inhibition, oncogenic BRAF signaling is coupled to TGF-β signaling, promoting melanoma progression and de-differentiation." (PMID 30979895, 2019). "However, co-expression of both mutant proteins promoted cellular dimerization of the catalytically inert BRAF D594A with the catalytically competent CRAF, inducing melanoma." (PMID 31398831, 2019). "Up to now, our national health insurance program does not yet cover BRAF inhibitor as the therapy for melanoma." (PMID 31890008, 2019). "Our findings demonstrate that in melanoma cells, upon cytokine stimulation, BRAF is subjected to nondegradable ubiquitination, primarily via the K27-linked polyubiquitin chains." (PMID 31015455, 2019). "We studied BRAF inhibitor responses using the BRAFV600E;Pten-hemizygous melanoma model." (PMID 31257073, 2019).
melanoma (continued). "As the BRAF inhibitor vemurafenib is—in contrast to melanoma—not effective in CRC, we combined it with the EGFR inhibitor gefitinib." (PMID 31861874, 2019). "Systemic therapy using BRAF-inhibitors with and without trametinib has resulted in encouraging outcomes for patients with melanoma BM." (PMID 31803366, 2019). "In addition, some drug therapies based on BRAF inhibition or combined BRAF and MEK inhibition against MM have been successfully applied in the treatment of melanoma (e.g. vemurafenib, trametinib, dabrafenib and vemurafenib with cotellic)." (PMID 30900145, 2019). "Additionally, combinatorial treatment of low‐dose magnolol and targeted therapy or chemotherapy led to an increase in cell death in BRAF‐ and NRAS‐mutant melanoma cells demonstrating a synergistic effect." (PMID 30793515, 2019). "Furthermore, knockdown of JNK1 and JNK2 in melanoma cells suppressed MEK and ERK activities, while BRAF protein levels remained unchanged." (PMID 31015455, 2019). "The FGF/FGFR signaling does not markedly contribute to the development of melanoma as it is suppressed by the overactivated RAS/BRAF/MEK/ERK (MAPK) signaling pathway." (PMID 31167513, 2019). "In conclusion, the PACMEL phase II trial found that adding the MEK inhibitor trametinib to paclitaxel chemotherapy significantly improved PFS and ORR in patients with BRAF-wt melanoma, but did not impact OS." (PMID 30428063, 2019). "In BRAF mutant melanoma cells, a non-specific phosphodiesterase inhibitor pentoxifylline activates the ER stress response resulting in the induction of autophagy and apoptosis." (PMID 30745871, 2019). "However, studies in BRAF mutant CRC and melanoma indicate that Wnt signalling can be activated upon targeting of BRAF48,49." (PMID 31097693, 2019). "Here, the authors describe that BRAF inhibition induces the autophagy-lysosomal function in BRAF-mutant melanomas via modulation of the TFEB and ZKSCAN3 transcriptome, which downregulates TGF-β and suppresses melanoma progression." (PMID 30979895, 2019). "Furthermore, despite initially impressive responses, BRAF and MEK-targeted therapies ultimately fail to cure most melanomas because of the emergence of therapy resistance." (PMID 31581557, 2019). "We report data from the testing of our novel PDE8A – C-Raf disrupter/HOXD12 conjugate (from here on, named PPL-008) in MM415, a B-Raf inhibitor resistant malignant melanoma cell line (MM415; BRAF wt, KRAS wt, NRAS Q61L) and in an MM415 melanoma murine xenograft model." (PMID 30909892, 2019). "BRAF and MEK1/2 inhibitors are effective in melanoma but resistance inevitably develops." (PMID 31727888, 2019). "Small molecule inhibitors of BRAF and MEK, a downstream protein immediately following BRAF, have been shown to confer a survival advantage for patients with BRAF V600E mutant advanced melanoma." (PMID 31217909, 2019). "Regarding melanomas, it would be important to determine the predictive value of MAF in the effectiveness of targeted therapies within a larger retrospective study, since our cohort study comprised only 3 cases treated with BRAF inhibitor." (PMID 31391014, 2019). "No head-to-head studies exist comparing BRAF inhibitor/MEK inhibitor (BRAFi/MEKi) combination treatments for BRAF-mutant melanoma." (PMID 31653096, 2019). "AKT3, but not AKT1 or AKT2, mediated the resistance to apoptosis in BRAF-targeted melanoma cells; promoted anchorage-independent growth in triple negative breast cancer; and controlled the VEGF-induced angiogenesis in ovarian cancer." (PMID 31470874, 2019). "Importantly, we have recently described experiments that functionally validated the role of four of these candidates (VAV1, MCF2, BRAF, RAF1) in driving vemurafenib resistance in human melanoma cell lines." (PMID 31208320, 2019). "By combining the Breslow thickness, mitotic count and BRAF immunohistochemistry, we identified a group of superficially spreading melanomas with an excellent survival probability independent of SNB status." (PMID 31039200, 2019).
melanoma (continued). "As melanoma is almost always associated with an activated MAPK pathway, even in tumours not driven by BRAF mutation, MEK inhibition is a promising therapeutic strategy." (PMID 30428063, 2019). "While KIT may not represent a reliable primary therapeutic target in melanoma due to it being mutated in a small fraction of lesions, its relevance as a target may be envisaged in the context of acquired drug resistance of BRAF-mutant melanoma treated with targeted therapies." (PMID 31635389, 2019). "PTEN gene alteration is not among the most frequent mutational events in melanoma (10%), but PTEN loss co-occurs with BRAF activating mutations (the key driver abnormality in melanoma) in 44% of BRAF mutant melanoma." (PMID 30925702, 2019). "To independently test the results from this screen, we treated the BRAF-mutant melanoma cell line A375M with siRNA targeting the non-coding region of MCL1." (PMID 31727958, 2019). "We next applied our algorithm to melanoma cell culture single-cell data, which contain transcriptomes of tumor cells derived from three patients: two replicates of wild-type (WT), BRAF mutant-NRAS WT, and BRAF WT-NRAS mutant samples." (PMID 31266885, 2019). "This combination was not predicted for any other melanoma genomic subtype, as vemurafenib and dabrafenib were only returned for the BRAF networks." (PMID 30820351, 2019). "In the present study, we showed that 1 was able to bind and stabilize G4 structures in vitro that form within the promoters of human KIT, BRAF, and BCL-2, which are three genes that may be relevant therapeutic targets in melanoma." (PMID 31635389, 2019). "They furthermore portray a CET resistance landscape resembling that of EGFR inhibitors in lung cancer or BRAF inhibitors in melanoma where non-genetic resistance can occur." (PMID 31287991, 2019). "Itacitinib is now in ongoing trials for metastatic solid tumors in combination with pembrolizumab (NCT02646748); NSCLC with Osimertinib (NCT02917993); and, BRAF-mutant melanoma with small-molecule MEK and BRAF inhibitors (NCT03272464), with outcomes yet to be reported." (PMID 31842362, 2019). "Although, there are example of combinations being better tolerated than single agents (BRAF plus MEK inhibitors in melanoma) this is unlikely to be observed in the vast majority of cases." (PMID 30777010, 2019). "When mutations occur in BRAF, downstream MEK and ERK are phosphorylated irrespective of RAS, resulting in melanoma-like cancer." (PMID 31307243, 2019). "Recent work shows that transcriptomic biomarkers can identify subgroups responding to combinatorial BRAF+MEK inhibitor treatment, but for those 50–60% of melanoma patients without BRAFV600E/K mutation, other suitable therapies are needed." (PMID 31253656, 2019). "Moreover, loss of NF1 expression has been observed in lung adenocarcinomas and melanomas that are resistant to treatment with EGFR and BRAF inhibitors, respectively." (PMID 30858928, 2019). "The patient populations in the current study and NEMO trial were different, as we included patients with neither NRAS- nor BRAF-mutant melanoma." (PMID 30428063, 2019). "With the recent introduction of the immune checkpoint inhibitors and selective tyrosine kinase inhibitors, including BRAF and MEK inhibitors, there has been a significant improvement in the progression-free survival (PFS) and overall survival (OS) of patients with melanoma." (PMID 31623313, 2019). "To this end, we found that compared with WT-BRAF, ubiquitination-deficient 5KR-BRAF failed to promote MEK/ERK activation in BRAF-depleted melanoma cells." (PMID 31015455, 2019). "Likewise, targeted treatment with BRAF and PI3K inhibition resulted in OXPHOS addiction in melanoma and glioma cells, ultimately conferring them with drug resistance." (PMID 30771209, 2019). "BRAF status was not predictive for overall survival of melanoma patients during immune checkpoint therapy." (PMID 30931305, 2019).
melanoma (continued). "The presence of BRAF or NRAS mutations does not confer an increased risk of malignant transformation, and further mutations are required to cause melanoma formation in a CMN." (PMID 30782194, 2019). "Only in two samples the panel was covered less than 90% but without involving the main targets for melanoma as BRAF and NRAS genes." (PMID 31547467, 2019). "Indeed, malignant melanoma cells exhibit elevated DNFA gene expression after the BRAF/MEK signaling pathway is blocked (e.g. by BRAF inhibitors), and DNFA expression remains higher in melanoma cells resistant to vemurafenib treatment than in untreated cells." (PMID 31316083, 2019). "Notably, many BCL-2 proteins are downstream factors of the RAS/BRAF/MAPK and PI3K/AKT signaling pathways, the activation of which contributes to the relapse of melanoma from treatment with targeted therapies." (PMID 31635389, 2019). "For instance, in melanomas inhibitors of mutant BRAF or immune checkpoint inhibitors did not decrease frequency of developing de novo CNS metastases, but improved patient survival." (PMID 31481958, 2019). "BRAF inhibitors are not so effective as compared to melanoma, because of various resistance mechanisms." (PMID 31661924, 2019). "This highlights that TFEB inactivation confers resistance rather than sensitivity to BRAF inhibition in melanoma." (PMID 30979895, 2019). "In addition to its antiapoptotic role in melanoma, STAT5 influences the sensitivity to anti-melanoma treatment, including interferon alpha (IFN-α) immunotherapy and BRAF inhibitors." (PMID 31569642, 2019). "In this phase II trial, adding trametinib to paclitaxel chemotherapy for BRAF-wt melanoma improved PFS and substantially increased ORR but did not impact OS." (PMID 30428063, 2019). "At the molecular level, melanoma can be classified into four main types: v-Raf murine sarcoma viral oncogene homolog B (BRAF)-mutant, neuroblastoma RAS viral oncogene homology (NRAS)-mutant, neurofibromatosis type 1 (NF1)-mutant, and triple-negative or wild-type melanoma." (PMID 31684113, 2019). "The BRIM8 study (NCT01667419) evaluated the effects of BRAF inhibitor vemurafenib monotherapy in patients with resected, BRAFV600-mutant melanomas and found that 1 year of vemurafenib was well tolerated but may not be an optimal treatment regimen." (PMID 31775797, 2019). "Likewise, vertical inhibition of MAPK signaling by combining BRAF and MEK inhibitors is now approved for BRAF‐mutant melanoma, but responses are transient and resistance to this combination is a pressing issue." (PMID 29650805, 2018). "Compound 110 was found to be the most promising inhibitor against the WM3629 melanoma cell line with IC50 value of 38.6 nM, which also showed enzymatic activities against wild-type BRAF and BRAF (V599E) kinase with IC50 values of 9.45 and 7.82 μM, respectively." (PMID 30373212, 2018). "Because USP28 is frequently deleted in melanoma and USP28 depletion leads to BRAF stability and enhanced MAPK kinase in HEK293T cells, we asked if interfering with USP28 expression conferred a similar response in BRAF (V600E) melanoma cell lines." (PMID 29880484, 2018). "Moreover, blocking E2F1 also induced death of melanoma cells resistant to BRAF inhibitors, and E2F1 inhibition increases sensitivity of melanoma cells to BRAF inhibitors." (PMID 29743521, 2018). "Notably, down-regulation of USP28 correlated with high BRAF levels in 75.4% (52/69) of melanoma tumors compared with 55% (16/29) of tumors which displayed both high USP28 and high BRAF (P = 0.023 and R= −0.18)." (PMID 29880484, 2018). "No significant percentage variations of MMP-9 serum levels were observed in melanoma patients at different times during the treatment with BRAF inhibitors (data not shown)." (PMID 30154717, 2018). "Unlike BRAF, NRAS mutations have been described at similar frequencies in melanomas arising in different skin areas." (PMID 30218391, 2018).
melanoma (continued). "Likewise, combining BRAF and BET inhibitors elicited synergistic anti‐tumor effects by in BRAF‐mutant melanoma." (PMID 29650805, 2018). "In addition, NFATc2, a transcription factor activated by oncogenic BRAF, was recently identified as a potent suppressor of MITF-PGC-1α in melanoma cells." (PMID 29629336, 2018). "A signature characterizing the pigmentation subtype of melanomas shows a bipolar expression pattern with high activity in the wt/wt cell culture and low activity in the BRAF-wt/NRAS-mut cell culture, and a fluctuating expression in BRAF-mut/NRAS-wt cells." (PMID 29614062, 2018). "For example, despite an absence of BRAF and lower abundance of RAS and KIT mutations in canine versus human mucosal melanoma, these tumors display likely MAPK activating events in 35% of cases." (PMID 30188888, 2018). "Myristoylated AKT3 has also been shown to partially protect melanoma cells from BRAF-inhibitor induced apoptosis without promoting MAPK activity." (PMID 30237495, 2018). "Epigenetic alterations may also contribute to altered MAPK signaling in melanoma, as observed with miR-524-5p, an miRNA that targets BRAF and ERK2 transcripts and is down-regulated in melanoma." (PMID 30166456, 2018). "Therefore, in both sensitive and resistant to BRAF inhibitor melanoma cells, mitochondria, and metabolism appear to be essential, and a drug, such as metformin or another biguanide, that alters this metabolism could be an interesting prospect for new melanoma treatments." (PMID 30186236, 2018). "Whereas single treatment only induced cell cycle arrest, the combination of quisinostat and flavopiridol induced apoptosis of melanoma cells and did so irrespective of their BRAF or NRAS status." (PMID 29464063, 2018). "Our current study also showed that ABCB5 was overexpressed in two of the BRAF inhibitor-resistant melanoma cells (A2058 PLXr and SK-MEL-28 PLXr) but not A375 PLXr cells." (PMID 29929490, 2018). "Our data show that both BRAF and NRAS mutant melanoma cell proliferation is reduced by lapachol." (PMID 29394289, 2018). "Oncogenic BRAF V600E has also been found to activate p90 ribosomal S6 kinase (RSK), which phosphorylates and activates PFKFB2, that then binds to 14-3-3 to promote glycolysis and melanoma cell growth." (PMID 30234009, 2018). "Single-cell RNA-seq data of three melanoma short-term cultures of BRAF/NRAS double wild type (wt/wt), BRAF-mutant/NRAS-wild type (BRAF-mut/NRAS-wt) and BRAF wild type/NRAS-mutant (BRAF-wt/NRAS-mut) cells were analyzed regarding PT dynamics to assess mechanisms of tumor progression." (PMID 29614062, 2018). "Unexpectedly, specific BRAF V600E inhibitors, such as vemurafenib that is highly effective in melanoma, do not benefit patients with CRC." (PMID 29193645, 2018). "Consistently, we find that knockdown of SOX10, the upstream regulator of FOXD3 also sensitizes mutant BRAF melanoma cells to Vemurafenib in vitro and in vivo, suggesting that SOX10 can protect melanoma cells against the acute cytotoxic effect of RAF inhibitors." (PMID 29295999, 2018). "Compared to V600 mutant BRAF single inhibition, combination inhibition of V600 mutant BRAF and MEK displayed elevated progression free and overall survival in clinical trials with metastatic BRAFV600 mutant melanoma patients." (PMID 29739364, 2018). "As opposed to melanoma, in which about 90% of BRAF mutations are located at amino acid position V600, approximately half of all NSCLC BRAF mutations are predicted to be non-V600." (PMID 29662630, 2018). "We treated 5 melanoma cell lines (2 NRASQ61 mutant: DO4, MM415; 3 patients derived BRAFV600E mutant: AV1, AV4, AV5) with increasing dosages of the MEK inhibitor trametinib and the BRAF inhibitor PLX4720." (PMID 30026510, 2018). "Further, our experiments indicate that BRAF inhibitors do not increase the death induced by inhibition of E2F1 in melanoma cells resistant to BRAF inhibitors." (PMID 29743521, 2018).